VPS18 (VPS18 core subunit of CORVET and HOPS complexes)
Description:
Plays a role in vesicle-mediated protein trafficking to lysosomal compartments including the endocytic membrane transport and autophagic pathways. Believed to act as a core component of the putative HOPS and CORVET endosomal tethering complexes which are proposed to be involved in the Rab5-to-Rab7 endosome conversion probably implicating MON1A/B, and via binding SNAREs and SNARE complexes to mediate tethering and docking events during SNARE-mediated membrane fusion. The HOPS complex is proposed to be recruited to Rab7 on the late endosomal membrane and to regulate late endocytic, phagocytic and autophagic traffic towards lysosomes. The CORVET complex is proposed to function as a Rab5 effector to mediate early endosome fusion probably in specific endosome subpopulations. Required for fusion of endosomes and autophagosomes with lysosomes. Involved in dendrite development of Pukinje cells (By similarity).
Synonyms: KIAA1475; PEP3
Tractability: Antibody: UniProt places it where antibodies can reach, with high confidence. PROTAC: ubiquitination databases record sites on it; its protein half-life has been measured.
Gene: Protein-coding gene on chromosome 15 (40,894,415 to 40,903,975, forward strand). Ensembl gene ENSG00000104142.
Subcellular location: Late endosome membrane; Lysosome membrane; Early endosome; Cytoplasmic vesicle, autophagosome; Cytoplasmic vesicle, clathrin-coated vesicle
Pathways (Reactome):
Disease: SARS-CoV-2 modulates autophagy
Gene Ontology:
Molecular function: molecular adaptor activity; protein binding; syntaxin binding; ubiquitin protein ligase activity; protein-macromolecule adaptor activity; actin binding
Biological process: autophagosome-lysosome fusion; endosome organization; endosome to lysosome transport; lysosome organization; negative regulation of intracellular estrogen receptor signaling pathway; protein ubiquitination; regulation of synaptic vesicle exocytosis; endosomal vesicle fusion; organelle fusion; regulation of SNARE complex assembly; intercellular transport; intracellular protein transport; vesicle-mediated transport
Cellular component: early endosome; glutamatergic synapse; HOPS complex; late endosome; late endosome membrane; lysosomal membrane; lysosome; CORVET complex; endosome membrane; actin filament; AP-3 adaptor complex; autophagosome; clathrin-coated vesicle; endomembrane system; presynapse
Genetic constraint (gnomAD): Loss-of-function variants: 25 observed, 80.4 expected, observed/expected ratio (o/e) 0.31, 90% interval 0.23 to 0.43. The upper end of that interval is the gene's LOEUF score, 0.43, which puts it in group 1 of 6, group 1 being the genes least tolerant of losing a copy. Missense variants: 1,168 observed, 1,336.8 expected, observed/expected ratio (o/e) 0.87, 90% interval 0.83 to 0.92. Synonymous variants: 523 observed, 559.53 expected, observed/expected ratio (o/e) 0.93, 90% interval 0.87 to 1.
Homologues: Orthologues: chimpanzee VPS18 (99% identical), macaque VPS18 (99% identical), rabbit VPS18 (97% identical), pig VPS18 (96% identical), guinea pig VPS18 (96% identical), mouse Vps18 (96% identical), dog VPS18 (95% identical), rat Vps18 (95% identical), zebrafish vps18 (66% identical), tropical clawed frog vps18 (61% identical), Drosophila melanogaster dor (36% identical), Caenorhabditis elegans vps-18 (27% identical). Paralogues in human: VPS11 (13% identical).
Diseases named in the same sentence as VPS18 in open-access papers:
VPS18 is named in the same sentence as 31 diseases in open-access papers, as found by Europe PMC text mining. Sharing a sentence is not in itself a finding about the gene and the disease. The quoted sentences say what the papers report.
glioblastoma (2 papers, 2025). The most malignant astrocytic tumor (WHO grade IV). "To further explore the molecular mechanism by which nintedanib regulates VPS18, we plan to conduct point mutation or multi-point mutation studies on key amino acid sites of VPS18 in glioblastoma models." (PMID 39859159, 2025). "In summary, our experimental results indicate that the effects of BIBF on glioblastoma cells are primarily mediated through VPS18." (PMID 39859159, 2025). "Furthermore, the expression level of VPS18 may be closely related to the malignancy and drug sensitivity of glioblastoma." (PMID 39859159, 2025). "In this study, we investigated the impact of VPS18 on the efficacy of BIBF in targeting glioblastoma (GBM) by transfecting VPS18-siRNA into U251 and U87 cells." (PMID 39859159, 2025). "By harnessing the biological characteristics of VPS18, synergistic drugs could potentially be developed in combination with BIBF in the future, thereby enhancing therapeutic effects on glioblastoma, particularly through targeting the autophagy pathway, which is especially crucial." (PMID 39859159, 2025).
glioma (2 papers, 2021 to 2025). A benign or malignant brain and spinal cord tumor that arises from glial cells (astrocytes, oligodendrocytes, ependymal cells). "Furthermore, the suppression of Circ-VPS18 significantly increases glioma responsiveness to the TMZ in vivo." (PMID 39877636, 2025). "Knockdown of VPS18 could repress the progression of glioma through sponging miR-370." (PMID 34194501, 2021). "A study showed that Circ-VPS18 expression was remarkably elevated in TMZ-resistant and glioma tissues." (PMID 39877636, 2025). "The interaction of Circ-VPS18 with miR-370 downregulates runt-related transcription factor 1 (RUNX1) expression, a member of the RUNX transcription factors with oncogenic properties, and subsequently accelerates the glioma growth as well as TMZ-resistance." (PMID 39877636, 2025).
lung carcinoma (2 papers, 2025). "Given that homozygous (but not heterozygous) Vps18 KO enhances lung tumor development in K-Ras mice, we further assessed the impact of VPS18 copy number loss and promoter hypermethylation on overall survival in patients with lung cancer harboring K-RAS mutations." (PMID 40615043, 2025). "Together, these findings provide the first in vivo evidence that Vps18 functions as a tumor suppressor in mammalian lung cancer." (PMID 40615043, 2025). "We then assessed the prognostic impact of VPS18 by analyzing gene expression data from 1411 patients with TCGA lung cancer." (PMID 40615043, 2025). "Our data show that Vps18 deficiency promotes lung tumorigenesis in K-Ras mice, and low VPS18 expression correlates with worse clinical outcomes in patients with lung cancer." (PMID 40615043, 2025). "To investigate the clinical relevance of VPS18 in human lung cancer, we first compared its mRNA expression between normal lung tissue (n = 75) and primary tumors (n = 560) using TCGA data." (PMID 40615043, 2025). "Our findings uncover a novel Vps18-EGFR-ERK axis in lung cancer and shed light on the design of new therapeutic strategies." (PMID 40615043, 2025). "Together, these results suggest that VPS18 downregulation contributes to lung cancer progression and serves as a poor prognostic marker, particularly in early-stage lung cancer." (PMID 40615043, 2025). "To explore the potential mechanisms underlying reduced VPS18 expression in human lung tumors, we analyzed VPS18 copy number variation (CNV) and promoter methylation in TCGA lung cancer samples." (PMID 40615043, 2025). "Our findings unveil a novel Vps18-EGFR-ERK axis in lung cancer and may inform the development of targeted therapeutic strategies." (PMID 40615043, 2025). "For lung cancer, further research is needed to clarify the conditions under which VPS18 expression influences outcomes, which may lead to novel therapeutic strategies and prognostic biomarkers." (PMID 40615043, 2025). "Here we identify Vps18 as a novel tumor suppressor in lung cancer." (PMID 40615043, 2025). "Furthermore, lung cancer patients with low VPS18 expression exhibit poor prognosis." (PMID 40615043, 2025). "Numerous studies have reported elevated VPS18 expression in various types of cancers, including prostate, bladder, and lung cancers, compared to adjacent non-cancerous tissues." (PMID 39859159, 2025).
ovarian carcinoma (2 papers, 2021 to 2023). A malignant neoplasm originating from the surface ovarian epithelium. "In addition, several other potentially interesting targets of YTHDF2 in ovarian cancer have been identified, such as the putative tumor suppressors TRERF1, ZDHHC14, DIS3L, Vps18, NOD1, and SLC9A8." (PMID 33658012, 2021).
congenital neutropenia (1 paper, 2026). "This study shows the pivotal impact of VPS18 for adequate vesicle dynamics during neutrophil development which might be relevant in the context of vesicle trafficking during granulopoiesis and congenital neutropenia." (PMID 41526335, 2026).
Dystonia (1 paper, 2024). An abnormally increased muscular tone that causes fixed abnormal postures. "Mutations in core proteins (VPS11, VPS16, VPS18, and VPS33) have been linked with multiple neurological disorders, including mucopolysaccharidosis (MPS), genetic leukoencephalopathy (gLE), and dystonia." (PMID 39000367, 2024).
malaria (1 paper, 2025). Malaria is a serious and sometimes fatal disease caused by a parasite that commonly infects a certain type of mosquito which feeds on humans. "Our data suggest that a CORVET-like or HOPS-like complex may play a role in endosomal trafficking in malaria parasites, but the specific subunits, besides the core VPS11 and VPS18, and the interaction with the corresponding Rab proteins, remains to be elucidated." (PMID 40198740, 2025).
osteosarcoma (1 paper, 2020). A usually aggressive malignant bone-forming mesenchymal neoplasm, predominantly affecting adolescents and young adults. "The second analysis of a locally recurring osteosarcoma of a 22‐year old female revealed an intra‐chromosomal rearrangement between NTRK3 and the VPS18 gene that was likely generated through chromothripsis of chromosome 15." (PMID 32022484, 2020).
parasitemia (1 paper, 2025). "To analyse the importance of the VPS11, VPS16 and VPS18 HOPS/CORVET core subunits for blood stage development, we monitored the parasitemia of synchronised cultures grown without (control) or in presence of rapalog over two replication cycles (4 days) using flow cytometry." (PMID 40198740, 2025).
sarcoma (1 paper, 2021). A usually aggressive malignant neoplasm of the soft tissue or bone. "Among these genes, only CCNDBP1 and VPS18 affect both the OS and DFS in patients with sarcoma, and the FC of CCNDBP1 is higher than that of VSP18 in our sequencing data." (PMID 34631521, 2021).
tauopathy (1 paper, 2023). Neurodegenerative disorders involving deposition of abnormal tau protein isoforms (tau proteins) in neurons and glial cells in the brain. "Intriguingly, at least three gene products, VPS18, NUSAP1, and EIF1AD, were found to be down-regulated in the AD brain, supporting their potential relevance in the emergence or propagation of tauopathy." (PMID 36316035, 2023). "Furthermore, we showed that VPS18, NUSAP1, and EIF1AD are all down-regulated in AD brain samples, supporting the notion that these regulators may be important for the development of tauopathy in the human brain." (PMID 36316035, 2023).
tumor (7 papers, 2021 to 2026). "Strikingly, expression of dominant-negative EGFR (dnEGFR) partially suppresses the tumor-promoting effects of Vps18 loss." (PMID 40615043, 2025). "Zebrafish Vps18 deficiency leads to hepatomegaly, skin hypopigmentation, and reduced retinal melanosomes." (PMID 40615043, 2025). "Together, these findings demonstrate that Vps18 deficiency promotes lung tumor development in mice by elevating EGFR protein levels within tumor cells." (PMID 40615043, 2025). "Notably, the tumor-promoting effects of Vps18 deficiency were partially rescued by expressing dnEGFR in mouse lung tumors." (PMID 40615043, 2025). "Together, these findings position VPS18 as a critical regulator of both tumor cell signaling and immune checkpoint control, implicating its dysregulation in the balance between tumor progression and immune evasion." (PMID 41516402, 2026). "VPS18 plays a dual role in regulating tumor progression and immune evasion through its functions in vesicular trafficking and receptor regulation." (PMID 41516402, 2026). "The dual roles of VPS18 in cancer biology—acting as either a tumor suppressor or a promoter—likely depend on tissue context, cancer type, and molecular environment." (PMID 40615043, 2025). "We show that Vps18 loss accelerates lung tumorigenesis in LSL-K-Ras mice, accompanied by enhanced tumor cell proliferation." (PMID 40615043, 2025). "Here, we identify Vps18 as an important tumor suppressor in murine lung tumorigenesis." (PMID 40615043, 2025). "Additionally, VPS18 contributes to cancer drug resistance, and its knockdown suppresses xenograft tumor growth." (PMID 40615043, 2025). "In terms of protective factors, up-regulation of VPS18 can promote tumor cell growth resistance to chemotherapy drugs, while silencing VPS18 gene can increase the resistance to DOX and DOC chemotherapy drugs, which seems to contradict the view as a protective factor." (PMID 38586328, 2024). "To determine whether Vps18 deficiency promotes tumor development by enhancing EGFR signaling, we investigated whether expressing dominant negative EGFR (dnEGFR) could suppress the lung tumor-promoting phenotype caused by Vps18 loss." (PMID 40615043, 2025). "However, the relationship between VPS18 expression and cancer prognosis varies across tumor types." (PMID 40615043, 2025). "Conversely, VPS18 has also been shown to suppress EGFR expression and lung tumorigenesis, suggesting a context-dependent tumor-suppressive function through modulation of growth factor receptor pathways." (PMID 41516402, 2026). "However, the mechanisms by which VPS18 influences tumor development remain unclear." (PMID 40615043, 2025). "Genetic ablation of Vps18 accelerates lung tumorigenesis in LSL-K-Ras mice, accompanied by enhanced tumor cell proliferation." (PMID 40615043, 2025).
cancer (5 papers, 2021 to 2025). A tumor composed of atypical neoplastic, often pleomorphic cells that invade other tissues. "The role of Vps18 in cancer is complex and context-dependent." (PMID 40615043, 2025).
VPS18 also shares sentences with these, for which no sentence is quoted: infection (3 papers); asthma (2); breast carcinoma (1); cancer of the brain (1); chronic obstructive pulmonary disease (1); COVID-19 (1); gastric cancer (1); glycogenosis (1); leprosy (1); liver carcinoma (1); lung adenocarcinoma (1); mucopolysaccharidosis (1); neurodegenerative disease (1); neurological disorders (1); thyroid cancer (1); type 1 diabetes (1); Zika virus infection (1); Zinc deficiency (1).